ZEB1 (zinc finger E-box binding homeobox 1)
Diseases named in the same sentence as ZEB1 in open-access papers (continued):
Sharing a sentence is not in itself a finding about the gene and the disease.
melanoma (continued). "Our results revealed the correlation between the ZEB1 expression and melanoma prognosis and suggested that targeting ZEB1 might be a potential method for treating melanoma." (PMID 36313708, 2022). "However, in contrast to the “MITF-low” GES, melanoma cells with the “EMT” GES showed high expression levels of EMT-TFs (ZEB1, SNAI1, and PRRX1), which have been demonstrated to play a critical role in melanoma progression." (PMID 35884783, 2022). "Furthermore, melanoma cells with FN1 expression are strongly associated with a pro-survival MITFlow state, upregulation of ZEB1 and hypoxia." (PMID 33870460, 2021). "ZEB1 was also reported as one of the mediators of SNAI2-induced EMT in melanoma." (PMID 33095806, 2020). "Similarly, in melanoma, high YAP and ZEB1 expression is associated with a more invasive gene expression signature and ectopic expression of YAP induces melanoma invasion both in vitro and in vivo." (PMID 32796736, 2020). "Moreover, two papers suggest a mechanistic link between TGF-β signalling and the Shh pathway in driving melanoma invasion in a ZEB1-dependent manner." (PMID 32796736, 2020). "However, in melanoma, an intrinsic balance between ZEB1 and ZEB2 seems to determine the cellular state by modulating the expression of the master regulator of melanocyte homeostasis, microphthalmia-associated transcription factor (MITF)." (PMID 32796736, 2020). "However, miR-200 expression levels are low in melanoma and regulation of ZEB1/2 was shown to be largely miR-200 independent." (PMID 32759677, 2020). "Overexpression of ZEB1 in melanoma short-term cultures is sufficient to drive switching towards a MITFlow undifferentiated phenotype bearing stem cell properties, characterized by increased expression of the neural crest stem cell (NCSC) marker NGFR, a major regulator of phenotype switching." (PMID 32759677, 2020). "ZEB1 was found to be a driver of malignancy in melanomas, resulting in poor patient outcome." (PMID 32998363, 2020). "ZEB1 has been proposed to be important for maintenance of the cancer stem cell (CSC) properties in the presumed CD133+/CD44+ cancer stem cell subpopulation in B16-F10 melanoma cells." (PMID 32796736, 2020). "In addition to FRA-1-driven oncogenic signaling, TGFβ was shown to promote the ZEB2/ZEB1 switch in melanoma cells." (PMID 32759677, 2020). "Moreover, SLUG and ZEB1 were both found to increase the migratory capacities of human melanoma cell lines in vitro." (PMID 32796736, 2020). "Moreover, this switch from ZEB2/SNAIL2 to TWIST1/ZEB1 was a significant factor of poor prognosis for melanoma patients." (PMID 32759677, 2020). "Basically ZEB2 is expressed in normal melanocyte, while ZEB1 is highly expressed in melanoma." (PMID 31275381, 2019). "In melanoma, the difference between ZEB1 and ZEB2 has been studied well." (PMID 31275381, 2019). "In melanoma, miR-205 represses expression of its direct target ZEB1." (PMID 30459436, 2018). "Furthermore, the expression levels of ZEB1/2 and E‐cadherin are inversely correlative and their expression levels can act as predictors of the epithelial phenotype of lung, melanoma, and other cancer cell lines." (PMID 29879296, 2018). "Additionally, overexpression of miR-200c in CD44+CD133+ CSCs resulted in downregulation of Zeb1 expression, reduction in cell proliferation, colony formation, cell migration and invasion as well as tumorigenic potential in melanoma." (PMID 28137308, 2017). "In addition, we confirmed that vemurafenib downregulates the invasive melanoma marker ZEB1, and upregulates the proliferative melanoma marker ZEB2." (PMID 28545079, 2017). "However, the ectopic expression of TWIST1 did not significantly stimulate the colony formation capacity of melanoma cell lines, suggesting that ZEB1 is a stronger oncogenic factor than TWIST1 in this tumor type." (PMID 27596438, 2016).
melanoma (continued). "Next, we investigated whether knocking down ZEB1 in initially PLX4032‐naive melanoma cell lines could increase their sensitivity to this drug." (PMID 27596438, 2016). "To further investigate the functions of ZEB1 in the modulation of melanoma cell plasticity and resistance to MAPKi, we selected two ZEB1high/MITFlow human melanoma cell lines (A375 and SKMEL5), two ZEB1low/MITFhigh short‐term cultures (C‐09.10 and GLO), and one ZEB1low/MITFhigh cell line (501MEL)." (PMID 27596438, 2016). "Our results thus demonstrate that ZEB1 is a major driver of phenotype switching‐mediated resistance to MAPKi and highlight that it is not the EMT phenotype or invasive status itself but the specific functions of EMT‐TFs that cause resistance in melanoma cells." (PMID 27596438, 2016). "Moreover, p75 mRNA expression was positively correlated with ZEB1 in melanoma samples from the TCGA (R = 0.29; P = 1.16E‐10)." (PMID 27596438, 2016). "We then analyzed the oncogenic functions of ZEB1 in melanoma cells." (PMID 27596438, 2016). "Moreover, ZEB1 expression level was increased in melanoma cell lines with acquired resistance to BRAFi and in biopsies from patients relapsing while under BRAFi treatment." (PMID 27596438, 2016). "As expected from previous data in melan‐a and B16F10 murine cells, ZEB1 knockdown in A375 cells prevented tumor initiation in nude mice, clearly demonstrating that ZEB1 is required for the tumorigenic capacity of melanoma cells." (PMID 27596438, 2016). "Furthermore, ZEB1 knockdown decreased the viability of resistant melanoma cells in both MITFlow and MITFhigh contexts, suggesting that ZEB1 partly functions through MITF‐independent mechanisms." (PMID 27596438, 2016). "As previously reported for their respective tumorigenic capacities, ZEB2 could therefore play an antagonistic function to ZEB1 in terms of resistance to treatment in melanoma." (PMID 27596438, 2016). "Consequently, the inhibition of ZEB1 sensitized naive melanoma cells to BRAFi, prevented the emergence of resistance following chronic exposure to BRAFi in vitro, and induced cell death in resistant melanoma cells." (PMID 27596438, 2016). "Furthermore, during melanoma progression transcriptional activity of ZEB1 is increased by Snail1 and Slug." (PMID 26517521, 2016). "We then examined whether the presence of ZEB1 was a requirement for the growth of malignant melanoma cells in vivo." (PMID 27596438, 2016). "Indeed, ZEB2 and SNAIL2 are expressed in normal adult melanocytes, and a switch in EMT‐TFs expression, characterized by a loss of ZEB2 and SNAIL2 and an upregulation of ZEB1 and TWIST1, occurs during melanoma progression." (PMID 27596438, 2016). "Interestingly, in this cohort, ZEB1 expression was higher in BRAFV600 or NRASQ61R‐mutated melanomas compared to BRAF/NRAS WT tumors, which corroborates the involvement of the MAPK pathway in the regulation of ZEB1." (PMID 27596438, 2016). "Similarly, MITF and BPTF co-repress SASP genes like SERPINE1, IL24, PDGFB, and CYR61 as well as ZEB1 that has a crucial role in melanoma progression." (PMID 26440048, 2015). "ZEB1 may drive a failsafe program for a melanoma cell to overcome the senescent state, exemplifying why ZEB1 expression in human melanoma is inversely correlated with MITF status." (PMID 25538895, 2014). "Therefore, we next combined the tumor vaccine B16F10/GPI-IL-21 with miR200c overexpression or ZEB1 knockdown in B16F10 cells to test the novel strategy for optimizing the therapeutic management of melanoma growth and metastasis in mice." (PMID 24625224, 2014). "Moreover, Gli2 cooperates with ZEB1 to transcriptionally repress of E-cadherin in melanoma, and TGF-β strongly enhances this complex formation." (PMID 25538895, 2014).
melanoma (continued). "Melanomas with a high proliferative index show high MITF expression; as SOX10 regulates the MITF pathway, it may suggest that invasion in oral melanoma occurs due to low MITF levels and high ZEB1 expression or through direct activation of the activity inhibitory melanoma (MIA) to invasion." (PMID 41012776, 2025). "Moreover, ZEB1 expression correlated with Tspan8 expression in patient melanoma lesions." (PMID 38398085, 2024). "The miR-126 inhibits invasion and migration in cervical cancer cells by binding to ZEB1; the miR-126-3p isoform was found to be associated with the transcription factor DYRK1B, and is involved in acquired resistance to dabrafenib in melanoma cells by regulating ADAM9 and VEGF-A." (PMID 39594467, 2024). "Similarly, the inhibition of SNAI2 or ZEB2 expression by siRNA, which led to an increase in ZEB1 expression, resulted in a significant reduction in cell stiffness correlated with an increase in the aspect ratio of melanoma cells and a decrease in circularity." (PMID 38398085, 2024). "We thus hypothesized that ZEB1 could be recruited on pTSPAN8 in melanoma cells." (PMID 38398085, 2024). "Overall, ZEB2/ZEB1 may not be associated with the acquisition of a given cell state but may regulate reversible transitions of melanoma cell state in a dynamic manner." (PMID 32759677, 2020). "Taken together with the results obtained following ZEB1 overexpression, our data indicate that ZEB1 drives the reversible conversion of MITFhigh/p75low differentiated into MITFlow/p75high stem‐like/initiating phenotypes, and regulates the subsequent tumorigenic capacity of melanoma cells." (PMID 27596438, 2016). "Finally, we investigated whether ZEB1 expression was necessary for the survival of resistant melanoma cells." (PMID 27596438, 2016). "Finally, we constructed a curated transcription factor (TF) and miRNA coordinated regulatory network, from which we identified downstream regulatory cascades initiated by three concordantly hypomethylated and up-regulated genes (PDGFD, ZEB1, and THRB) in NRASQ61-mutated melanomas." (PMID 25537510, 2015). "ZEB1 is an oncogene that may drive the development of malignant melanoma." (PMID 25537510, 2015). "Although it was reported that other transcriptional regulator, like HMGA2, can stimulate EMT, ZEB1 may function as the predominant trigger for EMT in melanoma cells, as overexpression of ZEB1 in melanoma cell was sufficient to revert cordycepin-mediated inhibition of EMT." (PMID 25868853, 2015). "For example, in a melanoma mouse model, ZEB2 inhibits cancer metastasis, whereas ZEB1 promotes tumor initiation and progression." (PMID 40356596, 2025). "ZEB1, a key transcriptional regulator of EMT in carcinomas, also plays a prominent role in the MES state of melanoma, repressing genes and facilitating an invasive behavior." (PMID 41429767, 2025). "Gene set enrichment analysis confirmed a metastatic signature in comparison to genes upregulated and downregulated in distant melanoma metastases, and identified pathway enrichment for NFKB, CDH1, and ZEB1 signaling." (PMID 40717170, 2025). "The DepMap survey also found significant direct relationships between SNAI1 and ZEB1 as well as SNAI2 and ZEB2 in melanoma cell lines, further supporting a potential role for snail and ZEB transcription factors in the CoREST-mediated phenotype switch." (PMID 38300709, 2024).
melanoma (continued). "EMT-TFs like SNAI1/2, ZEB1/2, and TWIST control the phenotype switching and are crucial for melanoma development." (PMID 38426087, 2024). "Of relevance, the microscopic analysis of the corresponding xenotransplants allowed the identification of clusters of MITF-/CDH1-/CDH2 + /ZEB1 + /CD271 + cells, supporting the existence of melanoma-initiating cells also in MM, as confirmed in clinical samples." (PMID 38191367, 2024). "E-Cadherin repression in a cell culture melanoma model is regulated by epithelial-mesenchymal transition (EMT) promoting transcription factors such as Slug, Zinc Finger E-Box Binding Homeobox 1 (ZEB1), Twist and Snail." (PMID 38419052, 2024). "ZEB1 expression was also found in intermediate states, including the SMC (Starved Melanoma Cell) phenotype." (PMID 38519642, 2024). "ZEB1 notably binds to the promoter of ZEB2 and represses its expression in melanoma cells, while these two factors are co-expressed in mesenchymal cells." (PMID 38519642, 2024). "To this end, we overexpressed ZEB1, leading to a decrease in E-cadherin expression and an increase in N-cadherin expression, or silenced SNAI2 or ZEB2 in melanoma cells in 2D cultures." (PMID 38398085, 2024). "We identified a positive correlation between ZEB1 and the Tspan8 expression level since ZEB1high melanomas were mainly associated with high expression levels of Tspan8 (five out of seven), contrary to ZEB1low melanomas, which showed low to no Tspan8 expression." (PMID 38398085, 2024). "For instance, Zhao and colleagues demonstrated, that shRNA-mediated knock-down of ZEB1 was correlated with a reduced migration and invasion ability of B15F10 melanoma cells." (PMID 38139138, 2023). "ISP significantly reduced the mRNA expression levels of SLUG, ZEB1, SNAIL1 and TWIST in A375 melanoma cells." (PMID 37504902, 2023). "First, we showed that JI130 and MEL56 inhibit cell migration in two invasive melanoma cell lines (MM029 and MM165) and downregulate the mRNA expression of the main EMT/invasion markers such as AXL, EGFR, MET, ZEB1, WNT5A, TGFβ, SNAI1, TWIST and MMPs." (PMID 37508519, 2023). "Correlating with this expression, expression of the mesenchymal maker, Zeb1, was also higher in APJ-KO melanoma and B16/apelin cells than in B16/WT cells." (PMID 36776217, 2023). "To examine the role of Zeb1 in the function of cDC1, we challenged WT and Zeb1-dcKO mice subcutaneously with 2 × 105 B16F10 melanoma cells." (PMID 37863917, 2023). "During melanocytic differentiation, both SLUG and ZEB2 act as tumor suppressor proteins whereas ZEB1 and TWIST1 are oncogenic proteins driving melanoma initiation and progression." (PMID 37370762, 2023). "For example, in melanoma, ChIP assays identified SLUG as a direct activator of ZEB1 with the ability to bind to E-boxes within the ZEB1 promoter." (PMID 37370762, 2023). "PD-L1 is regulated by various molecules, such as STAT3 in T-cell lymphoma and melanoma, STAT and AP-1 in classical Hodgkin lymphoma, the ZEB1 axis in non-small-cell lung cancer, PI3K in glioma, and Myc in multiple tumors." (PMID 36249036, 2022). "Melanoma phenotype switching has been proposed to be responsible for melanoma heterogeneity, controlled by cell-autonomous and microenvironment factors that impinge on MITF and EMT-TF regulation, particularly on ZEB1/2 and SNAIL1/2." (PMID 35267510, 2022). "For example, ZEB1 promotes the initiation and metastatic progression of melanoma which is supported by TWIST1, whilst ZEB2, supported by SNAI2, acts as a melanoma tumour suppressor." (PMID 35278142, 2022). "We found that YY1-knockdown melanoma cells were more sensitive to TGF-β1 stimulation, in that YY1 knockdown cells treated with TGF-β1, boosted the expression of the EMT genes FN1, CDH2, ZEB1, SNAI1 and VIM, among others." (PMID 35693944, 2022). "For the EMT transcription factors, both ZEB1 and ZEB2 showed overexpression in the RF models, especially ZEB2 expression in the melanoma-RF-FTMs." (PMID 36232952, 2022).
melanoma (continued). "Because these genes were lowed-expressed in melanoma tissues, but Hazard ratio of CS and SQLE were on the right side of 1 in the forest map, we selected CP and ZEB1 for the next analysis." (PMID 35232428, 2022). "For instance, in a mouse model of melanoma, ZEB2 inhibited tumor metastasis, while ZEB1 drove tumorigenesis and progression." (PMID 36076302, 2022). "To further elucidate the functional role of PKC-θ and ZEB1 in CD8+ T cells, we inhibited nPKC-θ with nPKC-θi2 in CD8+ T cells isolated from immunotherapy-responsive (CR/PR) or resistant (PD) melanoma patients." (PMID 35326747, 2022). "It has been proven that following the activation of the NRAS / BRAF pathway in melanoma, genes promoting cell proliferation such as SNAIL2 and ZEB2 are replaced by those regulating the migration such as ZEB1 and TWIST1." (PMID 35820816, 2022). "Mechanistically, ZEB1high melanoma cells showed a defective secretion of T cell-attracting chemokines, including CXCL10, suggesting the intrinsic role of ZEB1 in regulating the secretome and subsequent immune cell attraction." (PMID 35432344, 2022). "The high ZEB1/TWIST1, low MITF, high AXL state promotes an invasive, dedifferentiated phenotype in melanoma while the high ZEB2/SLUG, high MITF, low AXL state promotes an anti-invasive, proliferative, differentiated phenotype." (PMID 35008286, 2021). "ZEB2 silencing in mouse NRASQ61 melanoma cells decreases MITF, increases ZEB1, and induces proliferation defects." (PMID 32759677, 2020). "Specifically in melanoma, the transcription factor MITF is impacted by the EMT process, with ZEB1 and HIF1A being potent repressors of MITF expression." (PMID 32899370, 2020). "It is postulated that this process is one of the main reasons for the aggressiveness of human malignant melanoma and it has been shown that the transcription factors TWIST, ZEB1 and STAT3 are its main drivers." (PMID 32899370, 2020). "ZEB1 exhibited the highest correlation with that of GPC6 (r = 0.63, Spearman correlation) when all 389 melanoma samples were combined." (PMID 31199813, 2019). "In the TCGA melanoma dataset, the top 312 genes with a positive correlation (down to Spearman r = 0.5) with the prototypic EMT marker ZEB1, were also positively correlated with SNAI1, NFATc2, CDH2, and AXL, but negatively with MITF and CDH1." (PMID 30710146, 2019). "Cordycepin reduced the expression of the EMT factors in 72 melanoma patient samples comprising HMGA2, Twist1, and ZEB1, and the inhibition of HMGA2 sensitized gastric cancer cells to chemotherapy treatment." (PMID 29853899, 2018). "As anticipated, only a small subpopulation of melanoma cells expressed a combination of BRAFi-resistance markers (EGFR, ZEB1...) and an α-signature." (PMID 30429474, 2018). "In line with Denecker, which showed ZEB1 and ZEB2 inverse modulation and the presence of ZEB2 as a positive prognostic factor for melanoma patients, we observed the SCD5-dependent up-regulation of ZEB2 paralleled by reduced amounts of ZEB1." (PMID 29484133, 2018). "In particular, they show high expression of ZEB1 and Snail, two EMT-inducing transcription factors crucial for the acquisition of an invasive behaviour by melanoma cells." (PMID 28977999, 2017). "Levels of zinc finger E-box-binding protein 1 (ZEB1), a major driver of the EMT process in melanoma cells, were also significantly lower in the C10 clone." (PMID 27764776, 2016). "ZEB1 knockdown in sensitive ZEB1high A375 and SKMEL5 melanoma cells inhibited colony formation in soft agar, to a similar extent to that observed with BRAF inhibition (60%)." (PMID 27596438, 2016). "We found a strong inverse correlation between the mRNA expression of ZEB1 and MITF in melanoma cell lines from the Cancer Cell Line Encyclopedia (CCLE), regardless of their BRAF/NRAS mutational status (n = 61, P = 4.08E‐11)." (PMID 27596438, 2016).